E2F1 (E2F transcription factor 1)
Diseases named in the same sentence as E2F1 in open-access papers (continued):
Sharing a sentence is not in itself a finding about the gene and the disease.
gastric cancer (continued). "This study sheds light on the intricate HAGLR/miR-20a-5p/E2F1 ceRNA network active in gastric cancer, suggesting a fresh avenue for therapeutic intervention that may enhance patient outcomes." (PMID 39172101, 2024). "E2F1 may be crucial in the development of gastric cancer by influencing the cell cycle pathway and modulating its target gene MCM3, which may interact with MCM4, MCM5, and MCM7." (PMID 37594635, 2023). "In gastric cancer, miR-331-3p directly targeted E2F1 and induced cell growth defects." (PMID 38062510, 2023). "CircCYFIP2 regulates gastric cancer metastasis by mediating the miR-1205/E2F1 axis." (PMID 37160894, 2023). "Chen and colleagues demonstrated that NNT-AS1 could contribute to the tumorigenesis of gastric cancer by targeting E2F1 which served as a transcription factor and was an important regulator in cell cycle." (PMID 36270987, 2022). "Notably, based on KM plotter database analysis, high expression of E2F1 was identified as a potential indicator of poor prognosis of gastric cancer." (PMID 34564711, 2021). "Furthermore, it was also clarified that the effects of CHPF overexpression on the proliferation, colony formation, apoptosis, and migration of gastric cancer cells was significantly alleviated by the simultaneous knockdown of E2F1." (PMID 34564711, 2021). "Additionally, E2F1 was identified as a potential downstream target of CHPF in the regulation of gastric cancer, and its knockdown decreased the CHPF-induced promotion of gastric cancer." (PMID 34564711, 2021). "More importantly, the role of E2F1 in gastric cancer has been extensively studied." (PMID 34564711, 2021). "Further investigations showed that CHPF may promote the proliferation, colony formation, and migration and inhibit the apoptosis of gastric cancer cells through the regulation of E2F1." (PMID 34564711, 2021). "Moreover, miR-135a promoted the proliferation and invasion of oxaliplatin-resistant gastric cancer cells, and inhibited E2F transcription factor 1 (E2F1) induced apoptosis by inhibiting E2F1 and DAPK2 expression." (PMID 34422899, 2021). "The E2F proteins are encoded by eight genes (i.e. E2F1 to E2F8), each of which may play a specific role in gastric cancer." (PMID 34136392, 2021). "On the basis of these results, one could conclude that CHPF may promote the development of gastric cancer through the regulation of E2F1." (PMID 34564711, 2021). "MiR-218 could suppress gastric cancer cell cycle progression at G1 phase through CDK6/Cyclin D1/E2F1 axis in a feedback loop." (PMID 33330110, 2020). "To understand the mechanism underlying the cell cycle arrest of gastric cancer cells induced by knocking down AURKB, we next examined the effect of AURKB on various key cell cycle regulatory molecules, including CCND1, CDC16, CDC6, CDC26, CCNB2, CCNF, p27 and E2F1, in gastric cancer cells." (PMID 31982864, 2020). "To further verify that the downregulation of eIF3b indeed regulated the proliferation and metastasis of gastric cancer cells by affecting the expression levels of key genes, we selected E2F1, whose expression was dramatically decreased by eIF3b inhibition, to perform the rescue experiments." (PMID 31423012, 2019). "For example, transcription factor E2F1 activates lncRNA HOXA11-AS transcription in gastric cancer." (PMID 29642935, 2018). "Furthermore, miRNAs (miR-125a-5p, miR-331–3p, miR-17, miR-150, miR-155, miR-27b, miR-31, miR-92a and miR-509–5p), which differentially expressed in gastric cancer, were found to regulate expression of E2F1, E2F2, E2F5 and E2F7 in this study." (PMID 25646628, 2015).
gastric cancer (continued). "Because c-Myc and E2F1 activate each other's transcription, we checked whether Notch2 pathway suppresses miR-23b expression through E2F1 in gastric cancer cells." (PMID 26041881, 2015). "MiRNA-331–3p directly targets E2F1 and induced growth arrest of human gastric cancer cells." (PMID 25646628, 2015). "Moreover, qRT-PCR analysis detected the expression of E2F1 in 30 pairs gastric cancer tissues and found that E2F1 was upregulated in gastric cancer tissues." (PMID 24810364, 2014). "We proposed that upregulation of E2F1 promoted drug efflux in gastric carcinoma in vitro." (PMID 25466554, 2014). "Overexpression of E2F1 promotes the development of MDR in gastric carcinoma, suggesting that E2F1 may represent an efficacious target for gastric cancer therapy." (PMID 25466554, 2014). "Moreover, EBNA1, the only viral oncoprotein expressed in LCLs, all varieties of EBV-associated BL and other solid tumours such as nasopharyngeal carcinoma (NPC) and gastric carcinoma (EBVaGC), activates E2F1 expression at post-transcriptional level via PI3Kδ-dependent mRNA translation stress." (PMID 40773523, 2025). "Moreover, there are two contradictory reports demonstrating while BZLF1 can induce E2F1 expression in primary keratinocytes and gastric carcinoma cells, E2F1 along with c-Myc obstruct BZLF1 mediated transactivation through a negative regulatory element located at the N-terminal region." (PMID 40773523, 2025). "Besides, E2F1 could be a potential therapeutic target in various human cancers, such as the patients with gastric cancer, ovarian cancer." (PMID 37537694, 2023). "TUBA1C was proved to be a direct target of EGFR-AS1, and TUBA1C promotes gastric cancer proliferation, migration and invasion by accelerating the progression of the cell cycle from the G1 phase to the S phase and activating the expression of oncogenes: Ki-67, E2F1 and PCNA." (PMID 36941595, 2023). "Moreover, further investigation revealed that CHPF could promote proliferation and migration, and inhibit apoptosis of gastric cancer cells through the regulation of E2F1." (PMID 34564711, 2021). "In vitro assay illustrated that E2F1 could regulate the expression of stemness-associated genes, such as BMI1, OCT4, Nanog, and CD44, and maintain the tumor spheroid formation ability of gastric cancer cells." (PMID 33986804, 2021). "Besides, recent studies have identified the oncogenic role of E2F1 in gastric cancer." (PMID 33986804, 2021). "Moreover, E2F1 enhances expression of TINCR in gastric cancer cells." (PMID 32695943, 2020). "E2F1 is aberrantly expressed in gastric cancer (GC), and biology functions of E2F1 in GC are controversial." (PMID 28569791, 2017). "Moreover, deregulated E2F1 activity in gastric cancer may confer resistance to TGFβ-induced apoptosis through upregulation of the miR-106∼25 cluster that targets Bim." (PMID 26405162, 2015). "Finally, we found that GAS5 could influence gastric cancer cells proliferation, partly via regulating E2F1 and P21 expression." (PMID 24884417, 2014). "Finally, our observations suggest that E2F1 might serve as a molecular target for the therapy of MDR in gastric carcinoma." (PMID 25466554, 2014). "The oncogenic effects of E2F family genes (E2F1 and E2F7) in gastric cancer were at least partially mediated through transcriptional activation of MYBL2." (PMID 41491570, 2026). "E2F1 was a target of chondroitin polymerizing factor (CHPF), and silencing of E2F1 abolished CHPF-induced growth and migration in gastric cancer." (PMID 40221814, 2025). "In gastric cancer, YBX1 serves as a 5mC reader and stabilizer of ORAI2 mRNA, resulting in the upregulation of E2F1, promoting peritoneal metastasis and colonization of gastric cancer." (PMID 38255791, 2024). "In summary, HAGLR acts as an oncogenic lncRNA in gastric cancer, contributing to cell malignancy via the HAGLR/miR-20a-5p/E2F1 axis." (PMID 39172101, 2024).
gastric cancer (continued). "More importantly, a recent study emphasized that CHPF is able to regulate the expression of E2F1 through UBE2T‐mediated ubiquitination, thus promoting gastric cancer development." (PMID 38775031, 2024). "Differential expression analysis of TCGA gastric cancer data revealed that a pair of important ceRNAs, HAGLR-E2F1, were highly expressed in cancer tissue and significantly correlated with E2F1 expression." (PMID 39172101, 2024). "For example, lncRNA SNHG15 was upregulated in gastric cancer (GC) and E2F1 could interact with the promoter of SNHG15, leading to an increase in its expression." (PMID 39119602, 2024). "We demonstrate that CDK5 promotes apoptosis in gastric cancer cells by directly binding to DP1 and subsequently activating E2F1 signaling." (PMID 37990321, 2023). "For example, overexpression of E2F1 enhanced the resistance of paclitaxel combined with DDP and accelerated gastric cancer cell proliferation, while silenced E2F1 promoted the treatment efficacy of paclitaxel combined with DDP." (PMID 36864456, 2023). "Further analysis in vitro showed that TUBA1C influenced the expression of the oncogenes: Ki-67, E2F1 and PCNA, and promote malignant progression of gastric cancer cells by affecting the cell cycle." (PMID 36941595, 2023). "Similarly, silencing E2F-1 could, directly or indirectly, downregulate the expression of drug resistance-related genes to prevent cells from entering the S phase, finally reversing the multidrug resistance of gastric cancer cells." (PMID 35303867, 2022). "Inhibition of cell growth in cervical and gastric cancers by miR-331-3p was also reported via targeting NRP2 and E2F1 respectively." (PMID 34547721, 2021). "A positive correlation was observed between E2F1 and BMI1 (r = 0.422, p < 0.05), CD44 (r = 0.634, p < 0.05), OCT4 (r = 0.456, p < 0.05), and Nanog (r = 0.337, p < 0.05) in gastric cancer tissues." (PMID 33986804, 2021). "In gastric cancer, miR-218 was noted to inhibit cell cycle progression via the CDK6/CyclinD1/E2F1 axis." (PMID 34178650, 2021). "All these results suggest that E2F1 and CHPF share a similar role in gastric cancer, with E2F1 acting as a downstream target." (PMID 34564711, 2021). "For example, the TF E2F1 evokes the TINCR transcriptional activity and hastens gastric cancer progression through activating the TINCR/STAU1/CDKN2B axis." (PMID 34721660, 2021). "E2F1 and STAT3 have been reported to promote the transcription of Linc00668, respectively, in gastric cancer and in lung cancer." (PMID 32117742, 2020). "The results demonstrated that E2F1, E2F2 and E2F4 were overregulated in the gastric cancer samples compared with normal samples." (PMID 25646628, 2015). "To date, the members of E2F proteins include E2F1- E2F8 and among of them, E2F1, 2, 3, 4, 5, and 7 proteins were all significantly overexpressed in gastric cancer in the current study." (PMID 25646628, 2015). "The released E2F1 activates ANRIL expression, thus forming a positive feedback loop, continuing to promote gastric cancer cell proliferation." (PMID 24810364, 2014). "To examine the relationship between upregulation of E2F1 and acquisition of MDR in gastric carcinoma, we established gastric carcinoma cells that stably overexpressed E2F1." (PMID 25466554, 2014). "Here we found that in gastric cancer, PIN1P1 interacted with YBX1, upregulating its protein expression, which in turn enhanced the expression of PIN1, in which transcription factor E2F1 may be involved." (PMID 37929660, 2024). "The carbohydrate response element binding protein (CHREBP) is downregulated in gastric cancer and inhibits Cyclin D1 levels in gastric cancer cells in order to suppress growth via negative modulation of the Cyclin D1-Rb-E2F1 signaling mechanism." (PMID 36769170, 2023).
gastric cancer (continued). "In summary, our study described a double-negative feedback loop comprised of E2F1 and miR-532 in gastric cancer and emphasized the critical roles of E2F1 and miR-532 in GC proliferation, G1/S transition, DNA damage and apoptosis." (PMID 35440106, 2022). "In addition to c-Myc, E2F1 also activates BMI1 expression in neuroblastoma and gastric cancer cells." (PMID 36362068, 2022). "In gastric cancer, MIR31HG may suppress cell proliferation and hinder tumorigenesis partly by regulation of E2F1 and p21 expression." (PMID 32280307, 2020). "E2F1 could induce TINCR transcriptional activity and accelerated the progression of gastric cancer by activating the TINCR/STAU1/CDKN2B signaling axis." (PMID 32851080, 2020). "In a gastric cancer study, the regulatory axis of NNT-AS1/miR-424/E2F1 was confirmed." (PMID 33113895, 2020). "Furthermore, miRNAs differentially expressed in gastric cancer were able to regulate expression of E2F1, E2F2, E2F5 and E2F7, indicating that miRNAs-altered expression of E2Fs proteins is important factors in gastric cancer development or progression." (PMID 25646628, 2015). "Interestingly, silencing of miR-449a by ANRIL releases E2F1 expression, and, meantime, up-regulated E2F1 promotes ANRIL expression, thus forming a positive feedback loop, continuing to promote gastric cancer cell proliferation." (PMID 24810364, 2014). "E2F1 activates transcription of miR-106b, while miR-106b targets E2F1, constituting a negative feedback loop in gastric cancer cells." (PMID 23034144, 2012). "E2F1 activates transcription of miR-106b, while miR-106b targets E2F1, serving as a miRNA-directed negative feedback loop in gastric cancer cells." (PMID 21682903, 2011). "The miR-106b-25 cluster is involved in E2F1 posttranscriptional regulation and may play a key role in the development of TGF beta resistance in gastric cancer." (PMID 23554630, 2010). "Thus, E2F1 and miR-532 form a double-negative feedback loop that contributes to gastric cancer progression." (PMID 35440106, 2022). "Previous reports have demonstrated that the miR-106b-25 cluster (miR-106b, miR-93, and miR-25), which is activated by E2F1, can inhibit the growth-suppressing functions of TGF-β signalling by interfering with the downstream mediators p21 (CDKN1A, Waf1/Cip1) and Bim (BCL2L11) in gastric cancer." (PMID 31728016, 2020). "In addition, LINC00668 was a direct transcriptional target of E2F1, and LINC00668 could regulate gastric cancer cell proliferation both in vitro and in vivo." (PMID 27036039, 2016). "Indeed, we found that target genes regulated by E2F1 and E2F4 appeared quantities of differential expression in gastric cancer, which indicates that E2F1 and E2F4 are very likely to occupy an important share in growth of gastric cancer." (PMID 25646628, 2015). "According to stage classification, mRNA expressions of Notch2 receptor and Ets1 but not E2F1 were increased in stomach adenocarcinoma specimens from patients with gastric cancer advanced stages II–IV, compared with early stage I, whereas levels of miR-23b were decreased." (PMID 26041881, 2015). "Additionally, studies have indicated that miR-320d plays a role in regulating gastric cancer progression by modulating downstream FoxM, while exosomal lncRNA LINC00662 has been shown to promote non-small cell lung cancer progression by regulating the miR-320d/E2F1 axis." (PMID 39695099, 2024). "Our results suggest that E2F1-activated LINC00668, as a cell cycle regulator, enriches the mechanistic link between lncRNA and the E2F1-mediated cell cycle regulation pathway and may serve as a candidate prognostic biomarker and target for new therapies in human gastric cancer." (PMID 27036039, 2016). "Through high-throughput sequencing of SGC-7901 cells with or without CHPF knockdown, the present study identified E2F1 as a potential downstream effector of CHPF and revealed the possible mechanism by which CHPF regulates gastric cancer." (PMID 34564711, 2021).
gastric cancer (continued). "However, the mRNA expression of E2F1, cyclinD1 or P21 remained unaltered in the GAS5-overexpressed gastric cancer cells compared with the vector controls (data not shown)." (PMID 24884417, 2014).
lung carcinoma (105 papers, 2010 to 2025). "It is well documented that many cancers, including some lung cancers, have deletions or mutations in the retinoblastoma protein that result in increased levels of “free” E2F-1." (PMID 33652640, 2021). "Previous findings have confirmed that miR-20a can inhibit E2F1 directly, which is a transcription factor associated with the lung cancer cell growth, thus making miR-20a helpful for the early diagnosis of NSCLC." (PMID 25421010, 2014). "In lung cancer, elevated E2F1 was associated with invasion and metastasis of cancer cells." (PMID 39119602, 2024). "Therefore, CCNE1 and E2F1 have been confirmed to hold the potential to be diagnostic and prognostic markers in a variety of tumors, especially in lung cancer." (PMID 33613291, 2021). "Moreover, loss of E2F1 resulted in the development of reproductive tract sarcoma, lung cancer, and lymphomas in mice, collectively indicating a tumor suppressive role for E2F1." (PMID 29312618, 2017). "Overexpression of the E2F1 and its impact on cancer progression have recently been associated with miRNA deregulation in different types of cancer: melanoma, lung cancer, glioma and CRC, where marked reduction in expression was observed for MIR205, MIR493, MIR329 and MIR362, respectively." (PMID 28704519, 2017). "Contextual to this, the present study reveals the role of the transcriptional activator E2F1 in LUAD oncogenesis and its association with various biological characteristics of lung cancer stem cells (LCSCs)." (PMID 40886002, 2025). "E2F transcription factor 1 (E2F1) is a member of the cell cycle-related transcription factor family and can induce epithelial-mesenchymal transition in lung cancer and osteosarcoma cells." (PMID 40615041, 2025). "Analysis of TCGA data revealed significantly higher E2F1 expression in KRAS‐mutant lung cancer patients compared to those with wild‐type KRAS." (PMID 40936169, 2025). "For example, decreasing PLOD1 expression impairs the proliferation and colony-formation capacity of A549 lung cancer cells by the activation of E2F transcription factor 1 (E2F1)." (PMID 39530057, 2024). "ILF2 is upregulated in several malignancies, including liver and lung cancer, where its high expression stimulates malignant phenotypes in liver cells and interacts with E2F transcription factor 1 (E2F1) to promote lung cancer progression." (PMID 38622522, 2024). "E2F1 is overregulated in seven lung cancer datasets and is related to: 1) HPV infection; 2) HBV and EBV virus infection along with E2F3; 3) the cell cycle and pathways in cancer along with E2F3; and 4) HTVL-I infection along with E2F3 and TCF3." (PMID 39228892, 2024). "FOXM1 is overregulated in nine lung cancer datasets and is related to: 1) the negative regulation of transcription along with E2F1, FOXE1, and HMGA1; 2) cellular senescence along with E2F1, E2F3, and MYBL2; and 3) DNA repair and damage." (PMID 39228892, 2024). "To explore the interplay between MET, E2F1, and purine synthesis in clinical cases of lung cancer, we stratified them based on different percentiles of high and low gene expression into groups of low (25th percentile) and high (75th percentile) expression." (PMID 38957115, 2024). "As research technologies advance, there is immense potential to delve into the relationship between E2F1 and lncRNAs in lung cancer, leading to a more detailed understanding of lncRNA mechanisms." (PMID 39119602, 2024). "To confirm the pathological role of this E2F1/EPHB2 axis in lung cancer patients, we analyzed the expression of these genes in the TCGA lung adenocarcinoma cohort." (PMID 37980331, 2023). "In lung carcinoma, E2F1 is overexpressed and is a pro-oncogenic factor, controlling different malignant properties of cancer cells beside proliferation, such as migration, invasion, epithelial-mesenchymal transition and metastasis." (PMID 37980331, 2023).